CTLA4 (cytotoxic T-lymphocyte associated protein 4)
Diseases named in the same sentence as CTLA4 in open-access papers (continued):
Sharing a sentence is not in itself a finding about the gene and the disease.
sarcoidosis (continued). "Rather, a significant increase in CD25 and CTLA4 expression was found on circulating Tregs from sarcoidosis patients compared with healthy controls." (PMID 26376720, 2015). "In conditions such as sarcoidosis, checkpoint inhibitors, including PD‐1 or CTLA‐4, which are under investigation for cancer therapies‐might control hyperactive immune reactions and deter the development of granulomas." (PMID 41163525, 2025). "Moreover, further observations emphasize the role of CTLA-4 in immune dysregulation of other granulomatous diseases, like sarcoidosis, whose patients present decreased CTLA-4 expression on regulatory T cells." (PMID 39431514, 2024). "Proportions of CTLA4+ Tregs were increased in sarcoidosis compared with HCs." (PMID 38715030, 2024). "Interestingly, during sarcoidosis, the expression of cytotoxic T-lymphocyte antigen 4 (CTLA-4) is decreased, while the expression of programmed death-1 (PD-1) is increased in Th17-cells in the mediastinal lymph nodes." (PMID 37868478, 2023). "Moreover, T Regs and Th17 cells found in lymph nodes of patients with sarcoidosis have decreased CTLA-4 expression, leading to an altered balance of T Helper/T Reg and to an increased proportion of Th17." (PMID 35740604, 2022). "CD8+CTLA4+ percentages were higher in sarcoidosis than in HC (p = 0.0006) and MPA (p = 0.0481)." (PMID 36613701, 2022). "In this study, a similar reduction in CTLA-4 and PD-1 expression could be observed in sarcoidosis compared to a healthy individual." (PMID 28955342, 2017). "Furthermore, CD25 and CTLA4 expression (downstream molecules of FoxP3) were significantly increased on PB CD25int-highFoxP3high Tregs of sarcoidosis patients compared with healthy controls." (PMID 26376720, 2015). "Notably, anti-CTLA-4 and anti-PD-1 treatments have the potential to initiate or exacerbate sarcoid-like inflammation, reinforcing the notion of altered immune activation and possibly an autoimmune component in sarcoidosis." (PMID 28955342, 2017). "Therefore, increased CD25 and CTLA4 expression on sarcoidosis PB-derived Tregs could point towards increased apoptosis, counteracting their functionality." (PMID 26376720, 2015). "In line with previous work, we found an aberrantly activated phenotype of PB Tregs in patients with sarcoidosis, characterized by increased levels of CD25 and CD95 expression and increased proportions of CTLA4-expressing cells." (PMID 38715030, 2024). "Increased expression of CTLA4 and TIGIT, along with decreased expression of PD1, was reported on the T and NK cells of sarcoidosis patients compared with AAV patients and the HC group." (PMID 36613701, 2022). "The present study analyzed, for the first time, the CTLA4, PD1 and TIGIT expression on T and NK cell subsets in the peripheral blood of sarcoidosis, MPA and GPA patients." (PMID 36613701, 2022). "The PCA plot distinguished the disease clusters: MPA, GPA, sarcoidosis and HC showed that they were separated on the basis of CD4+CTLA4+, CD4+PD1+, CD4+TIGIT+, CD56, CD56+CTLA4+, CD56+TIGIT+, CD8, CD8+CTLA4+ and CD8+PD1+." (PMID 36613701, 2022). "The model showed CD56+CTLA4+ > 33.29% for 100% of sarcoidosis patients, but CD56+CTLA4+ ≤ 33.29, CD4+PD1+ > 1.55% and CD8+ > 30.7% for 100% of GPA patients." (PMID 36613701, 2022). "Recent cancer immunotherapies, including immune checkpoint inhibitors (targeting PD-1, PD-L1, or CTLA-4) and BRAF or MEK inhibitors were also reported as possible inducers of sarcoidosis-like reactions." (PMID 33330555, 2020). "Additionally, the combined deficiency of CTLA-4 on both TH17 cells and Treg cells may allow further activation of TH17 or TH17.1 cells while hindering Treg cell suppression, possibly explaining the increased TH17:Treg ratio found in sarcoidosis." (PMID 33036432, 2020).
sarcoidosis (continued). "There is some evidence that inhibition of CTLA-4 increases Th17 CD4+ cells in the peripheral blood, and there is also evidence that tissue samples consistent with sarcoidosis show increased infiltration of Th17 effector CD4+ cells in tissue." (PMID 30064495, 2018). "Manual gating of cells using FlowJo revealed higher frequencies of CTLA-4+ (4.9%) and PD-1+ (35.7%) CD4+ T cells in BALF from a healthy individual compared to sarcoidosis patients of both phenotypes." (PMID 28955342, 2017). "For instance, the dysregulated expression of co-inhibitory receptor cytotoxic T-lymphocyte antigen 4 (CTLA-4) in Th17 cells and T-regs in BALF and mediastinal lymph nodes of sarcoidosis patients possibly influences the local inflammation and is related to disease prognosis." (PMID 39062076, 2024). "Accordingly, in the present study, CTLA4 on peripheral NK cells was identified as the best clustering variable for sarcoidosis patients, rather than for HC, MPA and GPA patients." (PMID 36613701, 2022). "There is a significant decrease in cytotoxic T-lymphocyte antigen 4 (CTLA4) expression specifically on Th17 cells from mediastinal lymph nodes and BALF in sarcoidosis, contributing to Th17 priming and activation, and resulting in the ongoing active immune response in sarcoidosis." (PMID 34868074, 2021). "Several cases of ICI-induced sarcoidosis or sarcoid-like reactions have been described in the literature, mostly following treatment with anti-CTLA4 or anti-PD1, rather than anti-PDL1 or combination regimens." (PMID 32403289, 2020). "Sarcoidosis circulating Tregs displayed adequate expression of FoxP3, CD25 and CTLA4." (PMID 26376720, 2015). "Lack of CTLA-4 in these cells may contribute to their increased proliferation in the lungs of sarcoidosis patients." (PMID 33036432, 2020). "Therefore, we analyzed circulating CD25int-highFoxP3high Tregs of active sarcoidosis patients and healthy controls for expression of forkhead box P3 (FoxP3), CD25 and cytotoxic T lymphocyte antigen 4 (CTLA4) (three proteins pivotal for adequate Treg function) by flow cytometry." (PMID 26376720, 2015).
skin cancer (25 papers, 2013 to 2025). "Checkpoint inhibitors like PD-1 (programmed cell death protein 1) and CTLA-4 (cytotoxic T-lymphocyte-associated protein 4) inhibitors are commonly used in skin cancer treatment." (PMID 37803407, 2023). "Immune checkpoint blockade (ICB) targeting CTLA-4, PD-L1 and PD-1 have tremendously changed the field of oncological therapy including particularly skin cancers as tumors with a high mutational burden." (PMID 33291277, 2020). "Immune checkpoint blockade (ICB) targeting CTLA-4, PD-L1 and PD-1 has tremendously changed the field of oncological therapy and especially the treatment of skin cancers as tumors with a high mutational burden." (PMID 33291277, 2020). "When we performed subgroup analysis by cancer type, we found the CTLA-4 60G/A (rs3087243) polymorphism is correlated to significant increased skin cancer." (PMID 24376736, 2013). "The pooled results suggested the CTLA-4 60G/A polymorphism was significantly associated with an increased skin cancer risk (AA vs. GG: OR = 1.32, 95%CI = 1.09-1.59; AA vs. GA+GG: OR = 1.26, 95%CI = 1.07-1.48)." (PMID 24376736, 2013). "Additionally, cytotoxic T lymphocyte-associated protein 4 (CTLA4) has been investigated in another type of skin cancer, finding an inverse correlation between mRNA levels and promoter methylation, as should be expected." (PMID 35625975, 2022). "The pooled ORs for homozygote model comparison and recessive model comparison suggested the CTLA-4 60G/A polymorphism was significantly associated with an increased skin cancer risk (AA vs. GG: OR = 1.32, 95%CI = 1.09–1.59; AA vs. GA+GG: OR = 1.26, 95%CI = 1.07–1.48)." (PMID 24376736, 2013). "Immunotherapy, particularly PD-1 and CTLA-4 combination regimens, has markedly improved OS in skin cancers, with some patients achieving over five-year survival." (PMID 41527622, 2025). "Immunotherapy represents a significant advancement in treating skin cancers, primarily driven by the development of immune checkpoint inhibitors (ICIs) targeting PD-1, PD-L1, and CTLA-4 pathways." (PMID 41527622, 2025). "CTLA4 monoclonal antibodies have been validated as therapeutic agents and are effective for treating lung and skin neoplasms and recently in oral cancer." (PMID 40092547, 2025). "Some studies have established CTLA-4 as a critical molecule by regulating the development of UV-induced tolerance and, concomitantly, skin cancers, but its importance goes further to other cancers." (PMID 39194710, 2024). "Similar effects on endocrine organs, particularly the thyroid gland, are known from the use of PD1 or CTLA4 inhibitors in the treatment of skin cancer." (PMID 38068542, 2023). "It was reported that CTLA-4 gene palys an important role in UV-induced immune suppression as well as in development of skin cancer, transgenic mice that express a skin-specific CTLA-4 antagonist, developed fewer skin tumors after chronic exposure to UV." (PMID 24376736, 2013). "In addition, this T-cell cluster exhibited over-expression of exhaustion marker genes such as Tox, Pdcd1, Tigit, Havcr2, Lag3, and Ctla4 in the T cell cluster in skin tumors, suggesting the emergence of T-cell exhaustion in skin tumors." (PMID 40282557, 2025). "The greatest risk of all-grade PAEs in patients with skin cancer was related to anti-PDL1 plus targeted therapy drug, which differed significantly from the other interventions except for targeted therapy drug and anti-PD1 plus anti-CTLA4." (PMID 38373990, 2024). "The greatest risk of grade 3–4 PAEs in patients with skin cancer was from anti-PDL1 plus targeted therapy drug, which differed significantly from the other interventions except for anti-CTLA4 plus chemotherapy and anti-PD1 plus anti-CTLA4." (PMID 38373990, 2024). "Antibodies against cytotoxic T-lymphocyte-associated protein 4 (CTLA-4), programmed cell death protein 1 (PD-1) and programmed cell death 1 ligand 1 (PD-L1) are important state-of-the-art treatments, particularly for patients with metastasized skin cancer." (PMID 34073477, 2021).
skin cancer (continued). "In addition, according to a previous animal study CTLA4 mediates the effects of UV-induced immunosuppression, which is particularly important in the development of skin cancer." (PMID 31174203, 2019). "Finally, measurement of systemic levels of soluble PD-L1, PD1 and CTLA-4 may be of value in the selection of patients with skin cancer for immune checkpoint inhibitor treatment." (PMID 35223501, 2022).
squamous cell carcinoma (25 papers, 2016 to 2026). A carcinoma arising from squamous epithelial cells. "Across 908 squamous cell carcinomas, a high density of CTLA-4+ cells was linked to a positive HPV status (p = 0.0130)." (PMID 35091676, 2022). "Future research should address these gaps to fully elucidate the role of CTLA-4 variants in the development and progression of basal cell carcinoma (BCC) and squamous cell carcinoma (SCC)." (PMID 39194710, 2024). "For example, after the ACT immunotherapy, stem cell‐like squamous cell carcinoma cells upregulate CTLA4 through the expression of CD80, thereby directly inhibiting cytotoxic T cell activity." (PMID 37638338, 2023). "In the neoadjuvant scenario, a phase II clinical trial evaluated nivolumab activity with an anti-CTLA-4 agent compared to nivolumab monotherapy in 29 patients with squamous cell carcinoma in the oral cavity (OC-SCC)." (PMID 36140252, 2022). "High CTLA-4 expression in stromal cells independently influenced significantly better disease-specific survival in the squamous cell carcinoma subgroup, while CTLA-4 expression in metastatic lymph nodes had an independent negative prognostic impact." (PMID 35054356, 2022). "This study aims at investigating the presence and expression of specific checkpoint molecules such as PD-L1 and CTLA-4 in penile tumors of horses, particularly regarding malignant squamous cell carcinomas." (PMID 34359249, 2021). "Here, metastatic lymph node expression of CTLA-4 correlated with poor prognosis while soluble CTLA-4 expression predicted improved prognosis in squamous cell carcinoma." (PMID 33384695, 2020). "The proportions of PD-1+ and CTLA-4+ T cells were elevated in the squamous cell carcinoma when compared to the adenocarcinoma patients." (PMID 31010080, 2019). "Two homologous recombination genes, X-Ray Repair Complementing Defective Repair in Chinese Hamster Cells 3 (XRCC3) and RAD51 Paralog B (RAD51B) exhibited the highest correlation with CD274 and CTLA4 across all three squamous cell cancer types." (PMID 27683114, 2016). "More recently, chemoimmunotherapy with the anti-CTLA4 antibody ipilimumab + the anti-PD-1 nivolumab and two cycles of chemotherapy has been approved for clinical use, based on the results of the CheckMate-9LA trials (n = 224 squamous-cell carcinoma patients)." (PMID 39329995, 2024). "However, we carefully analyzed the clinical data and we found significant differences in the proportion of PD-1 and CTLA-4 molecules between squamous cell carcinoma (SCC) and adenocarcinoma (AD)." (PMID 31010080, 2019). "In squamous cell carcinoma, CD80 (FC = 0.88, P = .014), CTLA4 (FC = 0.80, P < .01), and IDO1 (FC = 0.84, P = .020) expression was lower in HRD cohorts compared with HRP." (PMID 41533995, 2026). "Concordantly, we observed higher expression of immune checkpoint proteins (CTLA4, TIGIT, and PDCD1) in the lymphocytes at the invasive front of squamous cell carcinomas." (PMID 41309580, 2025). "The established candidate gene lists were cross-validated in the respective other squamous cell carcinoma subtypes for the expression of CD274 and CTLA4." (PMID 27683114, 2016). "We examined the tumor microenvironments (TMEs) of keratoacanthoma (KA), squamous cell carcinoma (SCC), and common warts (VV), focusing on two interconnected immune factors: CTLA4, an inhibitory receptor crucial for T-cell homeostasis, and IFN-γ, a key antiviral and immunomodulatory cytokine." (PMID 40005446, 2025). "Metastatic initiating cells can also co-opt CTLA-4 immune checkpoint to avoid T cell activation—for instance, TGF-β-induced CSC expression of CD80, leading to T cell inhibition through the CD80-CTLA-4 axis in pre-clinical models of squamous cell carcinoma." (PMID 33498251, 2021).
chronic lymphocytic leukemia (24 papers, 2004 to 2024). "Recently, systemic administration of a human monoclonal antibody directed against cytotoxic T lymphocyte-associated antigen 4 (CTLA-4) expressed on circulating T cells in patients with chronic lymphocytic leukaemia (CLL) has been considered." (PMID 26490985, 2016). "Similarly, CTLA-4 319C/T polymorphism was found to be associated with decreased chronic lymphocytic leukemia risk." (PMID 39464701, 2024). "On the other hand, CTLA-4 has been observed in both the chronic and acute types of B-cell lymphocytic leukemia." (PMID 39456930, 2024). "Similar dependence of the response to a CTLA-4 blockade on the level of CTLA-4 expression was previously observed in chronic lymphocytic leukemia by our group." (PMID 36982802, 2023). "Aside from the expression of CTLA-4 on human B-cell chronic lymphocytic leukemia (discussed in ‘Tumors’ section), the expression of CTLA-4 on B1 and B2 B-cells has been sparsely studied but well-validated in mice and humans." (PMID 33384695, 2020). "T cells from patients with chronic lymphocytic leukemia (CLL) had abnormal upregulation of CTLA-4, which was positively correlated with an increased portion of Tregs and advanced Rai stage." (PMID 31186046, 2019). "CTLA4 downregulation led to a significant increase in the proliferation and survival of chronic lymphocytic leukemia cells." (PMID 28211499, 2017). "However, CTLA-4 involvement in chronic lymphocytic leukemia (CLL) and ALL have previously been reported." (PMID 35155232, 2022). "Consistently, we previously reported that CTLA-4 blocking antibody might be a beneficial form of immunotherapy for a subset of chronic lymphocytic leukemia (CLL) patients depending on the level of CTLA-4 expression on leukemic cells." (PMID 34502204, 2021). "Earlier, we reported that CTLA4 expression is inversely correlated with CD38 expression in chronic lymphocytic leukemia (CLL) cells." (PMID 23936412, 2013). "This study compares immune factors like PD-1/PD-L1, CTLA-4/CD86, CD200R/CD200, and EBV in chronic lymphocytic leukemia (CLL, a SID) and common variable immunodeficiency (CVID, a PID)." (PMID 37835480, 2023). "In previous studies, it was found that the chronic lymphocytic leukemia (CLL) patients who received ibrutinib treatment markedly diminished PD-1 and CTLA-4 expression on T cells and ibrutinib treatment augmented ICB in tumor models in Balb/c mice." (PMID 37735204, 2023). "In chronic lymphocytic leukemia (CLL), immunotherapy, such as anti-PD1/CTLA-4 immunotherapy, shows little benefits in patient survival, and the higher expression of LAG3 in CLL contributes to tumor immune escape, as well as indicates poor prognosis." (PMID 35111155, 2021). "While CTLA-4 was detected in both B-cell chronic and acute lymphocytic leukemia, it was reported only in T-cell acute and not chronic lymphocytic leukemia." (PMID 33384695, 2020).